ALK (ALK receptor tyrosine kinase)
Diseases named in the same sentence as ALK in open-access papers (continued):
Sharing a sentence is not in itself a finding about the gene and the disease.
melanoma (continued). "Furthermore, upregulated of ROS related signatures are observed in residual tumors from TKI‐treated patients with EGFR+ NSCLC, HER2+ breast cancer, and BRAF+ melanoma, suggesting that the findings of our study with ALK+ NSCLC cells may also possibly be observed in patients with ALK+ NSCLC." (PMID 39369284, 2025). "Additionally, vemurafenib-resistant melanoma cells-derived EVs could increase the proliferation of sensitive cells during vemurafenib therapy compared to the control cells via transporting an ALK isoform (truncated ALK fused with murine leukemia virus (MMLV))." (PMID 38778340, 2024). "Using an in vivo assay in A375-X1-resistant melanoma cell-transplanted mice, they first proved that treatment with combined BRAF and ALK inhibitors can stop tumor growth." (PMID 36831417, 2023). "Analogously to METi and EGFRi, the EML4-ALK translocation-based cellular model H3211 was exposed to the ALK inhibitor crizotinib (ALKi) and the BRAF V600E-addicted melanoma cell line G361 to the BRAF inhibitor (BRAFi) vemurafenib." (PMID 36494469, 2022). "In colorectal cancer/melanoma, the ALKBH5 inhibitor ALK-04 downregulated expression of VEGFA and TGFβ1, thus inhibiting angiogenesis and enhancing efficacy of anti–PD-1 therapy." (PMID 36291060, 2022). "NGS testing detected key driver alterations at expected prevalence rates: lung EGFR (16%), ALK (3%), RET (1%), melanoma BRAF (43%), colorectal RAS/RAF (67%), among others." (PMID 35323313, 2022). "Our findings support the role of ALK, ROCK1 and PHKA1 as a protein kinase for activating the metabolism of the energy sources from macronutrients used by the melanoma to support growth, proliferation and survival." (PMID 34199079, 2021). "Retrospective studies of spitzoid neoplasms have found activating fusions involving BRAF, RET, ROS1, ALK, or NTRK1 in 39% of melanomas with spitzoid morphology and just over 50% of Spitz nevi and atypical Spitz tumors." (PMID 32123303, 2020). "RAF1 fusion was detected in 4 cases (GC, melanoma, STS, and pancreatic cancer), BRAF fusion in 2 cases (BTC and STS), ALK fusion in 2 cases (CRC and BTC), ROS1 fusion in 1 case (CRC), and EGFR fusion in 1 case (CRC) with diverse counterparts." (PMID 32411236, 2020). "Rearrangements in several genes, including BRAF, RET, ROS1, ALK, NTRK1, and NTRK3, have been characterized in subsets of melanoma." (PMID 32123303, 2020). "Anaplastic lymphoma kinase (ALK), in exosomes secreted by BRAF inhibitor-resistant melanoma cells, has recently been demonstrated to transfer drug resistance by activating the MAPK signaling pathway in recipient cells." (PMID 32823989, 2020). "Increasingly, gene fusions involving various kinases, including ALK, ROS1, BRAF, RAF1, NTRK1, and NTRK3 have been identified within melanomas, and these fusion-positive melanomas often display spitzoid morphology." (PMID 32483240, 2020). "Within the input layer, representative examples for melanoma are the receptor tyrosine kinases (RTK), c-KIT, and anaplastic lymphoma kinase (ALK)." (PMID 29946532, 2018). "Here, we identified the overexpression of a novel truncated form of ALK, named ALKRES in the hereafter, as new mechanism driving acquired drug resistance in melanoma cells." (PMID 30290811, 2018). "An ongoing trial is currently recruiting patients to evaluate the use of entrectinib, a potent inhibitor of the tyrosine kinases ALK, TRKA/B/C, and ROS1, for the treatment of solid tumors, including melanoma (ClinicalTrials.gov identifier NCT02568267)." (PMID 28895885, 2017). "This has only just begun to be studied in the realm of cutaneous malignancies, with clinical trials currently ongoing for ALK-positive systemic ALCL and melanoma." (PMID 28895885, 2017). "In the old situation within specialised hospitals, we assumed that multiple single-gene tests were performed, minimally three for NSCLC patients (a multigene panel, HER2/EGFR, and ALK, ROS, RET, or MET) and two for melanoma patients (BRAF and NRAS or KIT)." (PMID 27899957, 2016).
melanoma (continued). "Rare tumors are addicted to single activated oncogenes, recently exemplified by bcr-abl in CML, ALK in 4% of NSCLC, and BRAF in certain melanomas." (PMID 23577104, 2013). "Therefore, for patients with ALK-positive NSCLC and BRAF V600-mutant melanoma, HSP90 inhibitor-based combination therapy is a promising strategy to overcome resistance and enhance therapeutic outcomes." (PMID 40872476, 2025). "The pertinent negative markers include histiocytic markers (CD163, CD14, CD1a, langerin), FDC markers (CD21, CD23, CD35, clusterin, CXCL13), hematolymphoid markers (CD45, CD3, CD20, CD79a), vascular markers (CD31, CD34), melanoma markers (melanA, SOX10, HMB45, S100), and others (ALK, CD30)." (PMID 40563703, 2025). "We found that TAE684 induced apoptosis in melanoma cell lines, which was consistent with the phenotype in Fyn-knockdown cells and involved a mechanism independent of its original target ALK." (PMID 41198656, 2025). "Other pertinent negative immunostains include hematolymphoid markers (CD45, CD3, CD20, CD79a), myoid markers (smooth muscle actin (SMA), desmin), vascular markers (CD31, CD34), epithelial markers (EMA, keratins), melanoma markers (melanA, SOX10, HMB45, S100), and other markers (ALK, CD30)." (PMID 40563703, 2025). "Similar to these findings with ALK+ NSCLC cells, it is reported that in DTP cells in EGFR+ NSCLC, HER2+ breast cancer, and BRAF+ melanoma, the gene signatures of ROS production are increased after treatment with clinically relevant TKIs and the expression of antioxidant genes is also decreased." (PMID 39369284, 2025). "Similarly, upregulation of NRG1 and HER3 expression was found to induce resistance to anaplastic lymphoma kinase (ALK) and BRAF inhibitors in melanoma and thyroid cancer." (PMID 37947595, 2023). "Overactivation of the WNT pathway in ALK+ ALCL tumors could inhibit the activity of therapeutics, such as anti-PD1 therapy (now in clinical trials) as suggested for melanoma treatment." (PMID 35246138, 2022). "TCGA analysis detected fusions in BRAF and RAF1 kinases in melanomas, but did not report fusions in ALK, ROS1, MET, RET, or NTRK, which are clinically targetable." (PMID 34831002, 2021). "It has been suggested that the oncogenic role of ALK is mediated via activation of tyrosine kinase, promoting the metabolism signalling cascade pathway of the melanoma and, sporadically, of other human cancer types, but not in normal tissues." (PMID 34199079, 2021). "For example, a Chinese study identified ALK break points in four patients among 30 acral melanomas (13.3%), and no ALK fusions were identified in 28 mucosal melanoma patients." (PMID 34831002, 2021). "Another NTRK/ROS1/ALK inhibitor (entrectinib) demonstrated clinical safety and efficacy in phase 1/2 trials, but no melanoma patients were included in these studies." (PMID 34831002, 2021). "Some ALK inhibitors (crizotinib, ceritinib, and alectinib) are now approved for clinical use in lung cancer, but not yet in melanoma." (PMID 29946532, 2018). "To date, no published studies have looked at the role of ALK inhibitors in the treatment of human melanoma." (PMID 28895885, 2017). "In fact, recent studies have explored the occurrence of ALK fusions in primary and metastatic cutaneous melanomas, but none out of 600 melanomas—including those positive for ALK expression—displayed the ALK translocation." (PMID 29156643, 2017). "Non-small cell lung cancer and melanoma are at the forefront of molecular diagnostics, with a variety of treatments targeting molecular alterations defining specific cancer subtypes (e.g., BRAF, EGFR, ALK alterations)." (PMID 25720744, 2015). "When all melanoma cell lines (n = 28) were considered, the three subtypes showed a significantly different response (FDR < 0.05) to the MEK inhibitor AZD6244, to the SRC family kinase (SFK)/ABL dual-kinase inhibitor AZD0530 and to the ALK inhibitor TAE684." (PMID 25742786, 2015).
melanoma (continued). "Moreover, HGF was also found to induce resistance to sunitinib, ATE684 (a selective ALK inhibitor), vemurafenib (the BRAF inhibitor, in BRAF-mutant melanoma), and lapatinib (a dual HER2 and EGFR tyrosine kinase inhibitor)." (PMID 23533466, 2013). "Genetic fusions involving anaplastic lymphoma kinase (ALK), neurotrophic receptor tyrosine kinase 1 (NTRK1), ROS proto-oncogene 1 (ROS1), rearranged during transfection (RET), and B-Raf proto-oncogene serine/threonine kinase (BRAF) genes are frequently observed in this type of melanoma." (PMID 39202970, 2024). "In addition, ALK expression was not as specific as the phosphorylation enzyme mRNA that presented high significance in melanoma cell lines from a neuroectodermal origin." (PMID 34199079, 2021). "It requires either mutated oncogene chimeric nucleophosmin/anaplastic lymphoma kinase (ALK) in T-cell lymphoma, Latent membrane protein-1 (LMP1) of Epstein–Barr virus in nasopharyngeal carcinoma, HDAC6 in osteosarcoma, NF-κB in melanoma or HIF-1α in pulmonary adenocarcinoma." (PMID 31480382, 2019). "Moreover, we show for the first time that the overexpressed ALKRES is secreted into extracellular vesicles (EVs) and is transferred to sensitive, ALK-negative melanoma cells." (PMID 30290811, 2018). "Markers of inflammatorymyofibroblastic tumor (anaplastic lymphoma kinase (ALK) protein) and perivascularepithelioid tumor (human melanoma black (HMB) 45 and Mel-A) were negative." (PMID 34287076, 2022). "In contrast to Spitz tumors with fusions of ALK, NTRK1, and ROS1, which are usually compound with a prominent epidermal component, epidermal involvement in the RAF1-fused melanomas was typically limited or absent." (PMID 32123303, 2020). "Immunohistochemical (IHC) staining was positive for human melanoma black-45 (HMB-45), Melan-A, and Ki-67 (LI 30 %), whereas staining for S-100 protein, cytokeratin (CK5/6, CK7), CD68, CD56, P63, TTF-1, P40, Napsin A, ALK D5F3, ALK D5F3 N, Syn, and CgA were negative." (PMID 27488496, 2016).
T-cell lymphoma (161 papers, 2006 to 2026). "In further support of an important role of IGF-IR in the pathogenesis of NPM-ALK+ T cell lymphoma, our current data show that acquired resistance to ALK inhibition is associated with a remarkable increase in the phosphorylation of IGF-IR." (PMID 31340850, 2019). "Our data suggest that STING may represent a novel marker for NHLs of T- or NK-cell lineage which can be used as a diagnostic marker for certain T-cell lymphomas with “null” cell immunophenotype (i.e., “null” cases of ALK-ALCL)." (PMID 35267494, 2022). "ALK+ ALCL is, by definition, a CD30-positive mature T-Cell Lymphoma (TCL) with aberrant expression of the ALK protein due to rearrangements of the ALK gene." (PMID 40565334, 2025). "Immunohistochemistry studies revealed the presence of disseminated T-cell non-Hodgkin lymphoma that was anaplastic lymphoma kinase (ALK)-positive." (PMID 38389588, 2024). "Another HSP90 client nucleophosmin/anaplastic lymphoma kinase (NPM/ALK) showed to induce PD-L1 via STAT3 activation in T cell lymphoma cells." (PMID 39148727, 2024). "HLs were diagnosed at a median age of 8.82 years and T-cell NHLs in patients aged 7.62 (ALCL CD30+/ALK+) and 8.20 (PTCL)." (PMID 37190220, 2023). "There were only two T-cell NHL cases: one diagnosed at 7.62 years (ALCL CD30+/ALK+), one at 8.20 years (PTCL)." (PMID 37190220, 2023). "ALCL is a rare aggressive peripheral/mature T-cell lymphoma in children and young adults, and is classified into ALK-positive (ALK+) and ALK-negative (ALK-) ALCL." (PMID 37731821, 2023). "HL occurred at a median age of 8.82 years, and T-cell NHL occurred in children with ages 7.62 (ALCL CD30+/ALK+) and 8.20 (PTCL)." (PMID 36551614, 2022). "By contrast, most T-cell lymphoma cell lines showed very high gene expression at the RNA level, with the highest levels being observed in the ALK+ and ALK-ALCL cell lines." (PMID 35267494, 2022). "Among T-cell NHLs, ALK+ and ALK-ALCL cell lines had the highest STING mRNA levels, whereas the HUT-78 cell line (Sezary syndrome) showed low levels." (PMID 35267494, 2022). "Reanalysis of published ROR2 expression datasets (GSE6338, GSE14879, GSE19069 and GSE65823)) displayed higher ROR2 expression levels in ALK+ ALCL samples compared with other peripheral T-cell lymphoma samples." (PMID 35246138, 2022). "Histological subtypes were DLBCL or transformed follicular lymphoma for 79 patients (77%), PMBL for 19 patients (18%), T cell lymphoma (NOS or ALK anaplastic lymphoma) for 5 patients (5%)." (PMID 33608849, 2021). "SUMO1–3 levels are upregulated in NPM-ALK+ T-cell lymphoma cell lines and ALK+ T-cell lymphoma patient tumors, whereas SENP1 levels are significantly downregulated." (PMID 34503213, 2021). "Autologous hematopoietic stem cell transplantation as front line consolidation in PTCL, NOS, ALCL, ALK-, ENKTL (disseminated), and enteropathy-associated T-cell lymphoma is recommended by expert consensus." (PMID 34072328, 2021). "In this regard, Marzec and colleagues demonstrated that HSP90 client protein nucleophosmin/anaplastic lymphoma kinase (NPM/ALK) induced PD-L1 surface expression via the activation of STAT3 in T cell lymphoma." (PMID 34917098, 2021). "Western blots performed on protein lysates show that all T-cell lymphoma cell lines examined (including ALK+ ALCL cell lines) express BRG1 at varying levels, whereas the acute T-cell leukaemia cell line JURKAT expresses BRG1 at higher levels." (PMID 35008316, 2021). "ALK+ ALCL is the most common subtype of T cell lymphoma in children and represents 10–30% of all lymphomas." (PMID 33348781, 2020). "Nucleophosmin-anaplastic lymphoma kinase fusion protein (NPM/ALK)-carrying T-cell lymphomas also strongly express PD-L1 via NPM/ALK-activated STAT3." (PMID 32992658, 2020).
T-cell lymphoma (continued). "STAT3 is a key regulator of the Treg cells phenotype with the expression of IL-10, TGF-β and FOXP3 of nucleophosmin/anaplastic lymphoma kinase (NPM/ALK)-carrying T cell lymphoma (ALK+TCL) cells." (PMID 32872659, 2020). "This phenomenon of PD-L1 upregulation has been reported in NPM-ALK-rearranged T-cell lymphoma and ALK-rearranged NSCLC." (PMID 32059449, 2020). "The findings presented herein are relevant not only to NPM-ALK+ T cell lymphoma but also to other types of cancer that simultaneously express ALK and IGF-IR." (PMID 31340850, 2019). "For instance, in anaplastic lymphoma kinase (ALK)-carrying T-cell lymphoma, PD-L1 expression can be induced by ALK signal transducer, and this function is also observed in signal transducer and activator of transcription 3 (STAT3) in chemoresistant NSCLC." (PMID 31636634, 2019). "T-cell lymphoma cells carrying the oncogenic nucleophosmin/anaplastic lymphoma kinase (NPM/ALK), which is involved in malignant transformation, induce high levels of PD-L1 expression via STAT3 and ERK activation." (PMID 31341011, 2019). "Of important note is that NPM-ALK+ T cell lymphoma cells resistant to ALK inhibition remained sensitive to IGF-IR inhibition." (PMID 31340850, 2019). "Anaplastic lymphoma kinase-expressing (ALK+) T cell lymphoma is an aggressive neoplasm that constitutes 3–5% and 40% of adults and children/adolescents non-Hodgkin lymphoma, respectively." (PMID 31340850, 2019). "In a previous study, we systematically characterized the in vitro effects of ASP3026, an orally available second-generation ALK inhibitor, in NPM-ALK+ T cell lymphoma cell lines." (PMID 31340850, 2019). "Combined targeting of IGF-IR and ALK is more effective than targeting IGF-IR or ALK alone in NPM-ALK+ T cell lymphoma." (PMID 31340850, 2019). "Initially discovered in T cell lymphoma, ALK is frequently affected in diverse cancers by oncogenic translocations." (PMID 31366041, 2019). "Nonetheless, our data show that inhibition of IGF-IR remained to be substantially effective in decreasing the viability of NPM-ALK+ T cell lymphoma cells resistant to ALK inhibition." (PMID 31340850, 2019). "The 5-year OS and PFS were 75% and 59% respectively for ALCL ALK positive, while for the remaining cases of systemic T-cell NHL were 30% and 26%." (PMID 29515769, 2018). "The oncogenic capacity of ALK rearrangement to upregulate PD-L1 expression was first documented in ALK-translocated T-cell lymphoma." (PMID 30060457, 2018). "In a more recent work, similar findings were observed when GSK1838705, a small molecule IGF-IR/IR/ALK inhibitor, was utilized to treat a variety of different cancers with high expression of IGF-IR, including NPM-ALK+ T-cell lymphoma." (PMID 27661006, 2017). "In this regard, IGF-IR and IGF-I are widely overexpressed in NPM-ALK+ T-cell lymphoma cell lines and in ALK+ lymphoma tumors from patients." (PMID 27661006, 2017). "Studies from our lab supported a role for IGF-IR in nucleophosmin-ALK-expressing (NPM-ALK+) T-cell lymphoma." (PMID 27661006, 2017). "Our study evaluated the serum levels of cytokines, especially Th2-associated cytokines, and analyzed their association with survival outcome in patients with nodal T-cell lymphomas including AITL, PTCL-NOS, and ALK+/- ALCL." (PMID 29100307, 2017). "Compared to other T cell lymphoma subtypes, ALK+ ALCL has a better prognosis, with a 5-year failure-free survival (FFS) rate of 60%." (PMID 28490385, 2017). "Previous studies demonstrating that OTX015 has pre-clinical activity in B-cell lymphomas were extended here to T-cell lymphomas, using a panel of five ALK+ ALCL cell lines (SUDHL1, TS-Supm2, L82, DEL, Karpass 299 and JB6)." (PMID 27793034, 2016). "A cooperative effect of OTX015 and ibrutinib in ALK+ ALCL provides the rationale to explore BET inhibitors in T cell lymphoma as well as in auto-immune disorders." (PMID 27793034, 2016).